MET (MET proto-oncogene, receptor tyrosine kinase)
Diseases named in the same sentence as MET in open-access papers (continued):
Sharing a sentence is not in itself a finding about the gene and the disease.
tumor (continued). "High levels of MET expression have been detected in MPM cell lines and tissues, where an autocrine loop seems to contribute to tumor angiogenesis." (PMID 37298116, 2023). "HGF plays a crucial role in promoting tumor progression, including the complete LIT-driven one, through the activation of the -MET pathway." (PMID 36831664, 2023). "Recent studies have highlighted that tumor-intrinsic PD-L1 signaling can be modulated by STAT3, AKT, MET oncogenic pathway, epithelial–mesenchymal transition, or BIM expression." (PMID 36894581, 2023). "Subsequent analyses answered fundamental questions such as prevalence rates in different tumor types, whether the fusions were enriched in any of these tumors, percentage of MET as the 3' partner and carriers of multiple fusions, location of the MET sequence, and breakpoints and partners." (PMID 37326363, 2023). "Induction of HGF and MET expression was observed in the progressing tumors and a cell line established from a TKI-resistant tumor exhibited acquired sensitivity to the MET inhibitor, crizotinib." (PMID 37470475, 2023). "The aberrant activation of c-Met and dysregulation of the MET/HGF pathway can lead to cancer cell proliferation, tumour growth, and metastasis." (PMID 37514101, 2023). "In this regard, sunitinib resistance can induce compensatory overexpression/activation of the receptor tyrosine kinases MET and AXL, as well as their transduction signaling in tumor cells." (PMID 36982721, 2023). "Treatment of cancer cells bearing an amplified, constitutively active MET oncogene with the MET kinase inhibitor JNJ-38877605 (indicated JNJ-605) blocks proliferation in vitro and halts tumour growth in vivo." (PMID 36697438, 2023). "The hypoxic environment can also induce the overexpression of the MET proto-oncogene and the activation of c-MET, amplifying the HGF signaling pathway and activating the transcription of hypoxia-inducible genes, ultimately increasing the stemness of the tumor." (PMID 37919751, 2023). "MET was a transmembranous tyrosine kinase receptor (TKR) in hepatocyte growth factor/MET (HGF/MET) pathway, and was well known as its critical role in pathogenesis of tumor." (PMID 36873946, 2023). "Consistent with human HCCs, RNAseq showed that c-MET/sgp53 mouse HCCs were characterized by activated c-MET and Ras/MAPK cascades and increased tumor cell proliferation." (PMID 37500626, 2023). "Binding to HGF, c-MET activates multiple downstream targets, such as the RAS/MAPK and phosphoinositide 3-kinase (PI3K)/AKT pathways, to drive tumor invasion and metastasis." (PMID 37500626, 2023). "In preclinical studies, telisotuzumab vedotin demonstrated significant tumor growth inhibition and regression in cell lines and PDX models with c-MET overexpression or MET amplification, by targeted delivery of toxins." (PMID 38162667, 2023). "While MET-CAR.CD28ζ is preferred for future development, the architecture of the CAR construct as well as strategies to compensate for tumor microenvironment-mediated CAR-T cell exhaustion are necessary to enhance MET-CAR-T cell therapeutic efficacy." (PMID 37779207, 2023). "Because MET downstream signaling overlaps with other receptor tyrosine kinases (RTK), emerging challenges for MET inhibitors include acquired resistance and tumor recurrence." (PMID 37779207, 2023). "In retrospective analyses, selected cancer-associated mutations and alterations that are putative targets of sitravatinib in vitro (e.g., RET, MET, CBL, AXL, KDR, and NTRK) were monitored from circulating tumor DNA in baseline plasma samples (n = 49)." (PMID 36842467, 2023).
tumor (continued). "In HER3/MET‐dKO SW1116 cells, in vitro cell proliferation and in vivo tumor growth were significantly inhibited and G0/G1 arrest was induced, indicating that simultaneous HER3/MET targeting was effective." (PMID 36751113, 2023). "Furthermore, potent c-Met inhibitors like crizotinib or cabozantinib were not used in this study, which might have provided insights into their feasibility to preclude metastatic behavior in particular in tumor cells showing high c-MET expression and concomitant high invasiveness." (PMID 36053327, 2023). "In this tumor type, CDK6 and FGFR2 were less expressed than in normal tissue, whereas CDK7, MET, ALK and AURKB stood out as upregulated in tumor samples." (PMID 36839989, 2023). "Our findings support the clinical application of DOXA as a safe and accessible treatment option for TNBC, particularly as both c-MET and EGFR are validated targets for neoplasms." (PMID 37924112, 2023). "Our results show that the frequency of inactivating CDKN2A/RB1 alterations is highest after tumor progression following post-operative combination therapy, and PDGFRA/MET alterations co-appear with CDKN2A inactivation." (PMID 37932833, 2023). "We confirmed MET expression in both Alb-R26Met and Myc-R26Met tumours, whereas high MYC levels were restricted to Myc-R26Met tumours." (PMID 36433941, 2022). "MET interacts with its ligand hepatocyte growth factor (HGF) and leads to NO-mediated tumor cell killing." (PMID 36555469, 2022). "In addition, we observed that NRAS, MET, and NFE2L2 mutations may predict early tumor recurrence." (PMID 34543520, 2022). "Coordination of tumor metabolism and autophagy is also critical for resistance to HGF/MET-targeted therapy." (PMID 36551686, 2022). "The proliferative type is mainly characterized by excessive activation of cell proliferation-related signaling pathways such as RAS/MAPK, MET, EGFR, ERBB2, and NOTCH; therefore, the tumor is more aggressive." (PMID 36578029, 2022). "Aberrant c-MET signaling promotes tumor progression and enables the development of distant metastasis by increasing the invasive capacity of HNSCC tumor cells." (PMID 35081970, 2022). "NSCLC patients with recurrent metastatic disease are subsequently eligible for targeted systemic therapy if the tumor expresses clinically actionable genetic alterations such as EGFR, ALK, MET, RET, and ROS1." (PMID 35448189, 2022). "RTKs that target MET, VEGFR-2 and AXL significantly increase the tumor suppressive effect and reduce the chance of tumor resistance to treatments." (PMID 36341335, 2022). "The current mandatory biomarkers to look for in late-stage NS-NSCLC include different genomic alterations present on EGFR, ALK, ROS1, NTRK, BRAF, MET, and RET, as well as the PD-L1 expression of tumor cells." (PMID 35565387, 2022). "Volatinib exhibits strong anti-tumor activity in GCPDX models, with overexpression of MET and phosphorylated MET (p-MET)." (PMID 35664756, 2022). "The combination regimen of trametinib and AXL/MET/VEGFR inhibitor glesatinib showed initial efficacy both in vitro and in vivo (92% reduction in tumor volume)." (PMID 35343367, 2022). "In recent years, it has been reported that activation of the MET/FAK signaling axis leads to CDK4/6-independent CDK2 activation, and the blockage of the three targets reduces cell proliferation and enhances tumor growth inhibition in vivo." (PMID 36430388, 2022). "Under expression of PTGS2 (READ) and PDGFRA (COAD and READ), over expression of MET & MMP9 (COAD and READ) were observed in the expression analysis using boxplots of genes between normal and tumor samples." (PMID 36110531, 2022). "Activated myofibroblasts are a key orchestrating cell population in post RF ablation distant tumor growth, primarily through induction of the HGF/c-MET/STAT3 axis." (PMID 35857766, 2022).
tumor (continued). "Blocking c-MET with cabozantinib and tivantinib induced a significant decrease in viability in the primary PeCa cell line UKF-PeC3 isolated from the tumor tissue as well as in cisplatin- and osimertinib-resistant sublines." (PMID 35406455, 2022). "Analysis of tumor specimens from advanced disease found increased expression of TrkB in a subset of samples, all of which had increased expression of HGF and c-MET." (PMID 36034555, 2022). "In line, pharmacologic or genetic inhibition of MET decreases RMS cell proliferation and migration in vitro and tumor growth and metastasis formation in vivo." (PMID 35574376, 2022). "Responses were observed in patients with RCC and NSCLC, and included patients with tumor RET rearrangements, and MET, CBL and AXL alterations." (PMID 35767205, 2022). "c-MET homodimerisation occurs following the binding of the hepatocyte growth factor (HGF) ligand, and RTK-mediated signalling leads to tumour proliferation and metastasis." (PMID 35144591, 2022). "Activation of the HGF/MET signaling pathway driven by a ligand (HGF)-dependent or ligand-independent manner promotes cellular proliferation, angiogenesis, tumor aggressiveness, and invasion, thereby resulting in poor survival outcomes." (PMID 34997350, 2022). "As the Ras/MAPK pathway regulated by RTKs played an important role in tumor metastasis, the function of EGFR/MET in regulating the Ras/MAPK pathway will be further investigated in our subsequent research." (PMID 35428350, 2022). "We further analyzed the role of DPP4, CTNNB1, and MET expressions in promoting THCA progression and tumor metastasis." (PMID 35205190, 2022). "A recent study found that combining abemaciclib, a CDK4/6 inhibitor, with merestinib, a c-MET inhibitor, reduced FOXM1 expression, and significantly inhibited tumor growth in metastatic UM tumors grown in human HGF-knock-in immunocompromised mouse models." (PMID 35954441, 2022). "CT053 (free-base form of CT053PTSA) inhibited MET, AXL, VEGFR2, FLT3 and MERTK phosphorylation and suppressed tumor cell angiogenesis by blocking VEGF and HGF, respectively, in vitro." (PMID 36341335, 2022). "In various tumor models, amivantamab efficiently downregulates the expression of EGFR and MET, and exhibited antitumor immunity with Fc-mediated effector interactions." (PMID 36432687, 2022). "HIF-1 can stimulate the hepatocyte growth factor (HGF)/HGF receptor (c-MET) signaling pathway, boosting tumor cell invasion and metastasis." (PMID 36591450, 2022). "Kinase profiling using KINOMEScan has revealed that, in addition to targeting FLT3/AURK signaling pathways, MET and AXL, two kinases that play a critical role in HCC tumor progression, invasion, and metastasis, were potently inhibited by DBPR114." (PMID 35062934, 2022). "Several sitravatinib targets, such as TAM receptors, MET, RET and KIT, are dysregulated in many types of cancer through overexpression or genetic alteration, and contribute to tumor development." (PMID 35767205, 2022). "In contrast here we have shown that targeting high frequency fusions such as TBL1XR1-PIK3CA, MET-MET, WHSC1L1-FGFR1 fusions offer much broader clinical utility across all tumour types." (PMID 35984852, 2022). "Inhibitors that target MET, AXL, VEGFR-2, FLT3 and MERTK are becoming research and development hotspots owing to their effect on promoting tumor development and progression." (PMID 36341335, 2022). "NOTCH and MET signaling have been demonstrated pro-oncogenic in RMS and their genetic or pharmacologic inhibition prevents tumor cell growth and survival in vitro and in vivo." (PMID 35574376, 2022). "For targeting receptor kinase signaling pathways including EGFR, HER2, HER3, and MET in tumor cells, GBR1302 has been developed as a T-cell engager to direct CD3-positive T cells to HER2 on tumor cells." (PMID 36432687, 2022). "Vandetanib inhibits MET phosphorylation and VEGF-1 induced by HGF.Cabozantinib induced phosphorylation of VEFGR2 plays an anti-tumor role." (PMID 36544713, 2022).
tumor (continued). "MET and its ligand HGF (hepatocyte growth factor) enhance tumor cells proliferation, invasion, and metastasis in HCC." (PMID 36080304, 2022). "Both the MET and AXL signaling pathway play crucial roles in HCC tumor progression, invasion, and metastasis, with their overexpression acting as predictors of poor prognosis in patients with HCC." (PMID 35062934, 2022). "The four most common fusions TBL1XR1-PIK3CA, MET-MET, WHSC1L1-FGFR1 and FGFR3-TACC3 representing 61% of all fusions were detected in a broad range of tumour types." (PMID 35984852, 2022). "c-MET and HGF were found to be expressed in tumor specimens and MB cell lines, and levels of c-MET mRNA correlated with poor clinical outcomes." (PMID 36034555, 2022). "The IL-6 target genes MET, IGF1, MMP3, CEACAM1, MMP1 and WNT5A were upregulated, which enabled the tumour cells to become invasive." (PMID 35022523, 2022). "CircPDE8A secreted by tumor cells can be released into the circulation via exosomes, regulate MACC1 as a miRNA-338 sponge, and promote invasion and metastasis through the MET/mitogen-activated protein kinase 1(MAPK1) or protein kinase B pathway." (PMID 35382838, 2022). "Of these, c-MET along with hepatocyte growth factor (HGF) activates RAS-ERK and PI3K-AKT pathways, strengthening tumour aggressiveness with poor prognosis." (PMID 36345011, 2022). "MET and VEGFR2 cooperate to promote tumor survival, thereby boosting angiogenesis via improved tumor blood flow and improved oxygenation." (PMID 35222436, 2022). "c-MET has been an important target against HNSCC because of its involvement in metabolic dysregulation, tumor-microenvirment and immune modulation." (PMID 35081970, 2022). "The interaction between MET and HGF in the TME promotes the recruitment of neutrophils and the production of NO, thereby leading to tumor cell death." (PMID 36514901, 2022). "HGF/c-MET signalling induces cell proliferation, differentiation, migration, invasion, and EMT, promoting tumourigenesis and tumour progression." (PMID 34976187, 2022). "PLTP and MET have been identified as potential biomarkers for LUAD diagnosis and in the evaluation of successful tumor excision." (PMID 36544145, 2022). "In this study, we demonstrate that CD44v6+ CSCs not only facilitate cancer stemness properties, such as self-renewal, tumor initiation, promotion of metastasis, and chemotherapy resistance, but also express high levels of the HGF/MET pathway." (PMID 36387747, 2022). "In particular, CZ has a unique anti-tumor immunomodulatory profile because several targets of CZ, including VEGFR2, MET, and the TAM kinases, play crucial roles in mediating the immunosuppressive tumor microenvironment in metastatic RCC." (PMID 36293494, 2022). "We detected the expressions of c-MET and HGF in the tumor tissues and paracancerous tissues and found much higher expressions of c-MET and HGF in tumor tissues than in the paracancerous tissues (P < 0.01)." (PMID 35874635, 2022). "Secondly, addition of HSP90 inhibitors have been shown to overcome resistance to MET TKIs in MET driven tumor models and SNX2112 has been shown to be effective as a single agent in a cell line with acquired MET TKI resistance." (PMID 35754026, 2022). "In this setting, c-MET is also induced by factor 1 inducible by hypoxia (HIF-1), and once activated, it can induce the expression of VEGF-A, further improving tumor angiogenesis." (PMID 35069735, 2022). "The AcSé program in France supported a multi-tumor phase II trial wherein 107 pediatric tumors were analyzed for alterations in the molecular targets of crizotinib (ALK, MET, and ROS-1)." (PMID 36034555, 2022). "Upregulation of HIF-1α also correlated with increased transcription of MET gene in PTC and ATC and correlated with tumor invasiveness." (PMID 35872981, 2022).
tumor (continued). "Furthermore, copy number changes are also emerging, affecting MITF or MET (MET proto-oncogene and receptor tyrosine kinase) (amplifications), or the loss of the suppressor PTEN, increasing the genetic diversity of the metastases as compared to the primary tumor." (PMID 35628196, 2022). "We demonstrate a requirement for the scaffold protein FRS2 downstream from both Met and FGFR1 and find that dual inhibition of MET and FGFR1 signalling results in TIC depletion, hindering tumour progression." (PMID 33772015, 2021). "For example, MET inhibitors significantly decreased the proliferation and increased the apoptosis of OCCC cells in vitro, and suppressed tumor growth in xenograft models of OCCC in vivo." (PMID 33525614, 2021). "Tumour shrinkage was generally greater in patients with HCC with MET overexpression; both patients who achieved PR had HCC with MET overexpression (n = 1, IHC 2+, 1,000 mg cohort, and n = 1, IHC 3+, 500 mg cohort)." (PMID 33972742, 2021). "Although osimertinib combined with crizotinib therapy showed dramatic tumor shrinkage in both the primary tumor and bone metastasis to an EGFR T790M-mutant NSCLC patient with MET amplification, the progression-free survival (PFS) was only two months." (PMID 34397683, 2021). "The ability of MET and FGFR1 signalling to compensate for one another in support of tumour growth has been identified in various human cancers." (PMID 33772015, 2021). "In the present study, we demonstrated that LMWF enhanced the suppressive effects of 5-FU on tumor cell migration in HCT116 and Caco-2 cells through the c-MET/MMP-2 signaling pathway." (PMID 34360807, 2021). "In these 76 patients, genomic profiling of 128 tumors by MSK-IMPACT yielded a median of 8 somatic alterations per tumor (range, 1–47), and a major oncogenic driver alteration (e.g., EGFR, KRAS, ALK, ROS1, or MET exon 14) was identified in 107 tumors (84%)." (PMID 34359558, 2021). "c-MET was found to be hyperactivated in HNSCC and has been reported to drive tumor progression, therapy resistance, and metastatic spread." (PMID 33919702, 2021). "By investigating the expression profiles of HGF and c-MET in all tumors in the TCGA database, we selected 11 solid tumors with significant differences in HGF or c-MET expression between tumor and normal tissues." (PMID 34261467, 2021). "The primary targets of CAB are MET (hepatocyte growth factor receptor, HGFR) and VEGFR2 (vascular endothelial growth factor receptor 2), which are both important mediators of tumor growth and tumor angiogenesis." (PMID 34067429, 2021). "Overall, these results show that both c-MET and ILEI cooperate for efficient MMP expression during growth of tumor xenografts and support the results from the cell-based assays." (PMID 33596971, 2021). "Mouse tumor models expressing a β4 mutant lacking its “signaling domain” (β41355T) have been instrumental in demonstrating its critical role in tumorigenesis and tumor-induced angiogenesis that depends on EGFR, HER2 or c-MET." (PMID 34778093, 2021). "HGF/c-MET signaling pathway (type X TKR) regulates cell proliferation, motility, and survival, also being a mediator of tumor growth and neo-angiogenesis." (PMID 33916438, 2021). "In SCC-9 cells, NR5A2 silencing downregulated the expression of MET, which is reported to be the downstream target gene of HK2 and responsible for HK2 induced tumor initiation and progression." (PMID 34277436, 2021). "Crosstalk between the oncogenic RTK hepatocyte growth factor receptor (MET), epidermal growth factor receptor (EGFR), and human epidermal growth factor receptor 2 (HER2) are involved in tumor resistance to RTK-targeted therapies." (PMID 32646879, 2021). "The HGF/c-MET signaling pathway regulates downstream PI3K/Akt/mTOR, Ras/MAPK, and JAK/STAT signaling pathways, which are important in regulating tumor cell growth, migration, and invasion." (PMID 34408780, 2021).